IL1B (interleukin 1 beta)
Diseases named in the same sentence as IL1B in open-access papers (continued):
Sharing a sentence is not in itself a finding about the gene and the disease.
triple-negative breast carcinoma (26 papers, 2017 to 2026). An invasive breast carcinoma which is negative for expression of estrogen receptor (ER), progesterone receptor (PR), and human epidermal growth factor receptor 2 (HER2). "Consistently, in an experimental model of triple-negative breast cancer, IL-1β deficient mice revealed significantly reduced levels of macrophages in the primary tumors, which were associated with limited tumor growth and an increase in infiltrating CD8+ T cells." (PMID 35631400, 2022). "Evidence shows that IL-1B boosts the invasive capabilities of triple-negative breast cancer (TNBC) cells, and knocking down OPG expression diminishes this effect." (PMID 39941709, 2025). "On the other hand, zerumbone has been shown to prevent IL-1β-induced invasion of triple-negative breast cancer cells by inhibiting the expression of IL-8 and matrix metallopeptidase 3 (MMP3)." (PMID 39769450, 2024). "We next examined the relationship between TIB density and IL-1β expression in invasive triple-negative breast cancer (TNBC) using tissue microarrays from 171 patients." (PMID 39801513, 2024). "A statistically significant increase in the content of MCP-1, IL-1β, IL-2, IL-4, and IL-10 was found in triple negative breast cancer." (PMID 36286034, 2022). "Interestingly, a recent study suggested that soluble CD44 released by triple-negative breast cancer cells promotes tumor progression by triggering macrophage IL-1β production." (PMID 35631400, 2022). "Triple-negative breast cancer (TNBC) induced TDO2 mRNA in co-culture with TNF-α and IL-1β This increase is through NF-κβ activation." (PMID 32050636, 2020). "By using in vivo and in vitro brain metastasis models, as well as human samples to study the role of the NLRP3 inflammasome in triple-negative breast cancer (TNBC) brain metastases, we found NLRP3 inflammasome components and IL-1β to be highly and specifically expressed in peritumoral astrocytes." (PMID 37749707, 2023). "Moreover, a clinical trial for triple-negative breast cancer is currently proceeding to test the checkpoint inhibitor PDR001 in combination with Canakinumab, an anti-IL-1β antibody." (PMID 33123472, 2020). "In contrast, no induction of IL-1β or IL-4 could be observed in the triple negative breast cancer cells (data not shown)." (PMID 28832545, 2017). "miR-483-5p has also been found to have a carcinogenic role in triple-negative breast cancer in that it inhibits SCOS3 (suppressor of cytokine signaling 3) gene expression that may trigger the pathway of STAT3, NF-κB, and primary inflammatory cytokines such as TNF-α, IL-6, MCP-1, and IL-1β." (PMID 37298699, 2023). "In triple-negative breast cancer (TNBC) cell lines, such as MDA-MB-436, MDA-MB-231, and BT549, higher basal levels of OPG and IL-1B were detected compared to non-TNBC lines like T47D and SKBR3." (PMID 39941709, 2025).
acute liver failure (25 papers, 2014 to 2025). Rapid deterioration of liver function causing encephalopathy and coagulopathy. "Inflammatory cytokines such as TNF-α, IL-1β and IL-6 are the key pathogenic factors of LPS/d-GalN-induced acute liver failure." (PMID 35645173, 2022). "In this study, SS pretreatment effectively reduced NO, TNF-α, IL-1β, and IL-6 secretion in paracetamol-induced acute liver failure." (PMID 34199606, 2021). "In a recent study, increased brain efflux of IL-1β, TNFα, and IL-6 was identified in patients with uncontrolled intracranial hypertension due to acute liver failure." (PMID 32178308, 2020). "TNFα and interleukin 1 beta (Il-1b) have been shown to be upregulated in brain tissue during acute liver failure in mice." (PMID 28801579, 2017). "Elevations of the proinflammatory cytokines interleukin (IL)-1β, IL-6, and tumor necrosis factor alpha (TNFα) are observed in both patients and in rodent models of acute liver failure." (PMID 27561705, 2016). "Similarly, several reports show an increased level of cytokines, such as IFN-Ɣ IL-1β, IL-12, IL-4, and IL-10 with ongoing AHE infection and HEV-associated acute liver failure." (PMID 34335528, 2021). "We have previously shown that chemokine ligand 2 (CCL2) is one pathogenic chemotactic cytokine that is elevated in neurons during hepatic encephalopathy due to acute liver failure and contributes to both microglia activation and the elevation of IL-1β and IL-6." (PMID 27561705, 2016). "Indeed, tumor necrosis factor-α, interleukin (IL)-1β, and IL-6 levels were increased in patients with acute liver failure as well as in rodent models of acute liver failure, and are thought to contribute to cerebral edema and intracranial pressure." (PMID 25012628, 2014). "In a mouse model of acute liver failure induced by D-galactosamine, the injection of mouse BM-MSCs significantly reduced the expression of the NLRP3 inflammasome protein and the production of pro-inflammatory cytokines associated with the progression of pyroptosis, IL-1β, and IL-18." (PMID 37894893, 2023). "In a previous study, MSCs reduced liver injury and lowered IL-1β, IL-6, and TNF-α levels in a lipopolysaccharide-induced acute liver failure rat model." (PMID 35765490, 2022). "In vivo studies in different acute liver failure (ALF) animal models have shown the existence of cell death by necrosis resulted in rapid IL-1α precursor release and upregulation of IL-1β and IL-18, leading to tissue injury with massive upregulation of anti-inflammatory molecule IL-1Ra." (PMID 40529491, 2025). "Moreover, it is found in peripheral blood mononuclear cell experiment in patients with acute liver failure (ALF) that, LPS stimulation increases IL-1β expression." (PMID 36227135, 2022). "The study on madecassoside found that it could ameliorate drug-induced acute liver failure by reducing inflammation (TNF-α ↓, IL-1β ↓, IL-6 ↓, iNOS ↓, COX-2 ↓) and oxidative stress (SOD ↑, CAT ↑, GPx ↑, Nrf2 ↑, HO-1 ↑)." (PMID 33013406, 2020).
Candida infection (25 papers, 2011 to 2025). "We measured the expression of two key proinflammatory cytokines (interleukin-1 beta and tumor necrosis factor alpha) and the zebrafish IL-8 homolog, each of which is associated with response to Candida infection." (PMID 40172223, 2025). "As a matter of fact, mice deficient for IL-1R (the receptor for IL-1β) are resistant and mice with hyper-functioning of the IL-1β signaling are susceptible to candidiasis." (PMID 22973279, 2012). "In the multivariable model for candidiasis status, built with median imputation, z-standardized predictors, and L2-penalized likelihood, higher salivary Candida albicans load and IL-1β emerged as independent risk markers, while higher salivary pH and flow were protective." (PMID 41301927, 2025). "Smokers are seven times more likely to have oral Candida infections, partly due to reduced IL-1β, IL-6, and TNF-α responses and nicotine’s enhancement of CA biofilm formation and adhesion." (PMID 41009855, 2025). "Logistic models revealed that C. albicans and IL-1β were significant predictors of candidiasis status, consistent with the role of fungal overgrowth and increased cytokine activity in exacerbating mucosal inflammation." (PMID 41301927, 2025). "IL-6 and IL-1β, both inflammatory cytokines, play a crucial role in inflammation in Candida infections." (PMID 39062060, 2024). "GSDMD inhibition alleviated candidiasis by preventing C. albicans escape from macrophages while maintaining inflammasome-dependent but GSDMD-independent IL-1β production for anti-fungal host defenses." (PMID 34795266, 2021). "Collectively, these results showed that IL-1β/IL-1R signaling is required for promoting mTOR activation and IL-17A induction in Foxp3+ cells during Candida infection in oral mucosa." (PMID 33240286, 2020). "In systemic candidiasis, for example, IL-1α increases leukocyte antifungal activity, while IL-1β recruits neutrophils." (PMID 31425553, 2019). "Concurrent administration of subtherapeutic doses of amphotericin B and a pentoxifylline analog led to increased survival times in experimental candidiasis in mice, whereas amphotericin B increased the expression of IL-1β in human mononuclear cells in vitro." (PMID 30275087, 2018). "Our results showed that, compared to HS PMNs, there was a slight reduction in IL-1β and IL-8 production after Klebsiella and Candida infection respectively, in all groups of MS patients." (PMID 26121651, 2015). "The components of the NLRP3 inflammasome as well as IL-1β, IL-18, and the IL-1α/IL-1β receptor IL-1RI, are important for host survival from systemic candidiasis and prevention of dissemination of oropharyngeal candidiasis." (PMID 24967821, 2014). "In our studies, in vivo IL-18 induction by Candida infection showed a similar pattern in mucosal tissues as IL-1β." (PMID 22174673, 2011). "Children with candidiasis showed significantly elevated salivary concentrations of IL-1β (34.5 ± 9.1 vs. 15.2 ± 5.8 pg/mL; p < 0.001), IL-6 (28.9 ± 8.3 vs. 12.4 ± 4.9 pg/mL; p < 0.001), TNF-α (36.8 ± 10.2 vs. 18.7 ± 6.2 pg/mL; p < 0.001), and IL-8 (41.5 ± 11.5 vs. 22.1 ± 7.3 pg/mL; p < 0.001)." (PMID 41301927, 2025). "Therefore, higher amounts of IL-1β produced by oral keratinocytes imply a greater possibility of injury to oral keratinocytes caused by a C. albicans infection, which may be associated with malignant transformation in individuals with oral carcinogenesis due to chronic Candida infection." (PMID 41294483, 2025). "Furthermore, Dectin-1-induced IL-1β protected against mucosal Candida infections becoming systemic and lethal." (PMID 33643264, 2021). "Thus, our study supports that IL-1β/IL-6 imbalance is central to Foxp3+ cell plasticity and inflammation control during Candida infection." (PMID 33240286, 2020). "Therefore, we next investigated these cytokines in the context of MyD88/IL-1β signaling and Treg functions during Candida infection in aged mice." (PMID 33240286, 2020).
Candida infection (continued). "Collectively, these results show that tongue immunopathology could be ascribed to an impairment of IL-1β and excessive production of IL-6 during oral Candida infection in aged mice." (PMID 33240286, 2020). "Our results imply that Candida infection in the context of IL-1β/IL-6 imbalance may lead to an inappropriate accrual of dysfunctional IFN-γ+Foxp3+ cells." (PMID 33240286, 2020). "The IL-1β dependency for Th17 differentiation has been already reported in Candida infection." (PMID 31425553, 2019). "Importantly, when applying an in vivo systemic candidiasis model, we observed reduced IL-1β levels in mice infected with the ece1Δ/Δ mutant as compared to mice infected with wild-type cells." (PMID 30323213, 2018). "However, IL-1β may play a key role during systemically disseminated Aspergillus infection, as was described with systemic Candida infection." (PMID 33643264, 2021). "IL-1β production is required for an effective host response to Candida infection, and mice lacking critical inflammasome components such as NLRP3, ASC, or caspase-1 are hypersusceptible to C. albicans-induced sepsis." (PMID 34795266, 2021). "We show that inflammasome driven IL-1β responses via both the NLRC4 and NLRP3 inflammasome are essential for epithelial antimicrobial peptide production, and other inflammatory responses including IL-18 and IL-17 in response to Candida infection." (PMID 22174673, 2011).
cutaneous leishmaniasis (25 papers, 2012 to 2025). Leishmaniasis affecting the skin. "IL-1β, a cytokine associated with various inflammatory diseases, has also been associated with the pathogenesis of cutaneous leishmaniasis." (PMID 34691019, 2021). "Inflammatory IL-1β was associated with the severe form of difuse cutaneous leishmaniasis caused by L. mexicana." (PMID 28591228, 2017). "This study for the first time demonstrated polymorphism in the gene IL-1β −511 in Mexican-mestizo patients from Tabasco, a state with high prevalence of patients with cutaneous leishmaniasis." (PMID 22629474, 2012). "In fact, prolonged inflammasome activation has been associated with IL-1β mediated pathology in cutaneous leishmaniasis, suggesting that neutrophil microbicidal phenotype may also contribute to drive tissue damage on susceptible background." (PMID 39378227, 2024). "Inflammasome markers IL‐1β+ and IL‐18+ were significantly higher in cutaneous leishmaniasis (p < 0.05)." (PMID 40947759, 2025). "Cutaneous leishmaniasis (CL) is an infectious disease characterized by severe local inflammatory response, predominantly mediated by cytokines such as IL-1β and TNF, and cytotoxicity, contributing to tissue damage and lesion development." (PMID 41200163, 2025). "During cutaneous leishmaniasis (CL), intermediate monocyte are reported to be a source of inflammatory cytokines IL-1β and TNF, and they express CCR2 attracting them to sites of inflammatory pathology." (PMID 38669292, 2024). "From the results of DisGeNET, the hub genes IL10, IL6, CXCL8, CSF2, IFNG, IL1B, and TNF were causing Visceral Leishmaniasis; IL10, IL4, CXCL8, IFNG, IL1B and TNF found to cause Cutaneous Leishmaniasis and Urban Cutaneous Leishmaniasis." (PMID 36989283, 2023). "IL-1β has many roles in the immune response, but the pathologic role of IL-1β in cutaneous leishmaniasis appears to be when the cytokine is in excess." (PMID 33841444, 2021). "Using a combination of murine models and human studies we and others have shown that the skin microbiome enhances IL-1β and IL-17A production and contributes to increased pathology in cutaneous leishmaniasis." (PMID 34699567, 2021). "This is the case in cutaneous leishmaniasis, where excessive cytolysis leads to inflammasome activation and subsequent production of the proinflammatory cytokine IL-1β." (PMID 33793565, 2021). "IL-1β/IL-1R signaling is crucial for P2Y2R-mediated protective immune response in an experimental model of cutaneous leishmaniasis." (PMID 33061823, 2020). "In the present study, we investigated caspase-1/IL-1β axis activation in the protective immune response induced by P2Y2 receptor activation in an experimental model of cutaneous leishmaniasis." (PMID 33061823, 2020). "IL-1β/IL-1R signaling was crucial to P2Y2R-mediated protective immune responses in an experimental model of cutaneous leishmaniasis." (PMID 33061823, 2020). "Since blockade of this cytokine does not affect IFN-γ production or parasite control, our studies identify anakinra or monoclonal antibodies that specifically block IL-1β (such as canakinumab) as potential therapeutics for treatment of cutaneous leishmaniasis." (PMID 28192528, 2017). "In summary, this work reveals a previously unrecognized link between CD8+ T cell mediated cytotoxicity and the well-known pathway of IL-1β mediated inflammation, which has important implications for patients with severe forms of cutaneous leishmaniasis." (PMID 28192528, 2017). "The aim of the present study was to determine single nucleotide polymorphisms of IL-1β (−511), CXCL8 (−251) and IL-1RA (+2018) in patients with cutaneous leishmaniasis infected with Leishmania mexicana." (PMID 22629474, 2012). "In the present study, we investigated the involvement of the P2Y2 receptor in the activation of NLRP3 inflammasome elements (caspase-1 and 11) and IL-1β secretion during L. amazonensis infection in peritoneal macrophages as well as in a murine model of cutaneous leishmaniasis." (PMID 33061823, 2020).
cutaneous leishmaniasis (continued). "The association of reduced lesion size and increase in pro-inflammatory gene expression is interesting, particularly given that a recent study suggests that in mice, NLRP3 inflammasome activation and IL1β production could contribute to CD8 T cell mediated pathology in murine cutaneous leishmaniasis." (PMID 32109251, 2020). "An interesting study done with monocytes from cutaneous leishmaniasis patients revealed NLRP3 inflammasome activation and IL-1β production after stimulation with L. braziliensis antigens." (PMID 31961876, 2020). "Using a combination of murine models and studies in cutaneous leishmaniasis patients, we have identified the NLRP3 inflammasome and IL-1β as components of the pathologic response that occurs as a consequence of CD8+ T cell cytotoxicity in severe forms of leishmaniasis." (PMID 28192528, 2017). "Even though elevated levels of mRNA IL-1β have been reported in biopsies of patients with American cutaneous leishmaniasis, neither IL-1β (−511), CXCL8 (−251) nor IL-1RA (+2018), have been associated with disease in leishmaniasis." (PMID 22629474, 2012). "Furthermore it has been reported that IL-1β−/−C57BL/6 mice, infected with Leishmania major, were resistant to experimental cutaneous leishmaniasis." (PMID 22629474, 2012). "The analysis of IL-1β production revealed that non-stimulated monocytes from patients with cutaneous leishmaniasis had a significant increase of their production of IL-1β when compared with healthy controls (p = 0.015)." (PMID 22629474, 2012). "In cutaneous leishmaniasis, CD68+ macrophages correlated positively with inflammasome markers, whereas in mucocutaneous leishmaniasis, CD163+ cells showed strong negative correlations with IL‐1β and caspase‐1." (PMID 40947759, 2025).